PDK4 (pyruvate dehydrogenase kinase 4)
Diseases named in the same sentence as PDK4 in open-access papers (continued):
Sharing a sentence is not in itself a finding about the gene and the disease.
type 2 diabetes (20 papers, 2008 to 2024). "For example, previous work has shown that pharmacological inhibition of FOXO1 can ameliorate cardiac defects associated with type 2 diabetes by suppressing PDK4 and thereby increasing PDH activity." (PMID 38769106, 2024). "PDK4 encodes pyruvate dehydrogenase kinase 4 and is overexpressed in skeletal muscle in patients with type 2 diabetes, fasting, and immediately post exercise." (PMID 36516485, 2022). "In this study, we observed PDK4 expression decreased in diabetic skin and fibroblasts, but there is literature that states that the level of PDK4 is elevated in patients with type 2 diabetes and in animals and humans on a HFD." (PMID 38001078, 2023). "These interventions include the use of the PDK4 inhibitor dichloroacetate, and chemical inhibition of FoxO1 transcriptional activity (which drives increased PDK4 expression in type 2 diabetes), both of which improved diastolic function in diabetic rodents." (PMID 35924321, 2022). "In type 2 diabetes, up-regulation of PDK4 also inactivates PDC, which promotes gluconeogenesis and thereby contributes to the hyperglycemia characteristic of this disease." (PMID 35642195, 2022). "In the mouse model of Type 2 diabetes, liver insulin receptor substrates 1 and 2 are deleted, and additional knockout of PDK4 gene can improve blood glucose control and glucose tolerance." (PMID 33739396, 2021). "In type 2 diabetes, decreased levels of insulin promote an increase in both PDK4 gene expression and PDK2 mRNA levels." (PMID 28298922, 2017). "Therefore, PDK4 has complex relations to comorbid conditions of type 2 diabetes, cardiovascular disease, and other conditions that are common in military personnel and impact their morbidity." (PMID 25983695, 2015). "Importantly, PDK4 expression is increased and its methylation decreased in type 2 diabetes." (PMID 36525084, 2023). "Overall, our data suggest that Pdk4 may be a useful therapeutic target for type 2 diabetes." (PMID 23940800, 2013). "In type 2 diabetes, the two isoforms PDK2 and PDK4 are induced in a tissue-specific manner." (PMID 28298922, 2017).
ovarian carcinoma (17 papers, 2020 to 2025). A malignant neoplasm originating from the surface ovarian epithelium. "There were only 4 PPAR-TRGs (AP2A2, DOCK4, HSDL2, and PDK4) out of 269 DEGs, which are associated with platinum chemosensitivity in ovarian cancer." (PMID 33613670, 2021). "The data indicated that PDK4, highly expressed in ovarian cancer tissues, was associated with poor patient outcome." (PMID 32390009, 2020). "Additionally, PDK4 loss in ovarian cancer could activate the EMT and thus encourage cancer cell invasion and migration." (PMID 37296697, 2023). "In ovarian cancer, the loss of FAM210B was found to reduce the expression of pyruvate dehydrogenase kinase 4 (PDK4) and glycolysis, promoting epithelial-to-mesenchymal transition (EMT), migration, and invasion." (PMID 39900908, 2025). "Serous ovarian tumours showed significantly higher expression of PDK4, compared to non-serous tumours, supporting a significant correlation between upregulation of PDK4 and ovarian carcinoma progression." (PMID 32390009, 2020). "By IHC, the presence of PDK4 in whole ovarian tumour suggested the role of PDK4 in regulating not only stemness but also cancer properties in ovarian cancer." (PMID 32390009, 2020). "Our data collectively supported the potential utility of PDK4 as a therapeutic target for management of ovarian cancer driven by ascites-derived CSCs." (PMID 32390009, 2020). "Mechanistically, we have determined the signalling pathways by which PDK4 regulates tumorigenesis and stemness of ovarian cancer." (PMID 32390009, 2020). "PDK4 directly enhances cell proliferation, invasion, and chemoresistance in ovarian cancer." (PMID 34793335, 2022). "The clinical significance of PDK4 in ovarian cancer was further determined." (PMID 32390009, 2020). "In addition, we found that PDK4 mRNA was upregulated in ovarian cancer cell lines (SKOV3, OVCAR3, OVCA420, TOV112D and OVTOKO), compared to the normal human ovarian surface epithelial cell line, HOSE 96-9-18, by qPCR." (PMID 32390009, 2020). "Moreover, higher PDK4 was correlated with shorter overall and progression-free survival, implicating its utility as a novel prognostic marker for ovarian cancer." (PMID 32390009, 2020). "The role of PDK4 in ovarian cancer properties will be determined in future studies." (PMID 32390009, 2020). "A phosphokinase array was performed to elucidate the mechanism by which PDK4-regulated stemness in ovarian cancer using ALDH+CD44+ SKOV3 cells transiently transfected with siPDK4 or control siRNA, and ImageJ analysis was applied to quantify the intensity of the spots on the arrays." (PMID 32390009, 2020). "Clinically, a positive correlation was detected between PDK4 immunoreactivity and advanced tumour stages, grades and serous histological subtypes, as well as metastasis, highlighting a potential role of PDK4 in ovarian cancer progression and aggressiveness." (PMID 32390009, 2020). "In addition, PDK4 protein expression was higher in tumourspheres from ascites-derived tumour cells and ovarian cancer cell lines, as determined from immunoblot analyses." (PMID 32390009, 2020). "Moreover, significantly higher immunostaining of PDK4 was observed in metastatic foci than in the corresponding primary tumours from 16 pairs of FFPE tissue sections (p < 0.01), supporting association of PDK4 with metastasis in ovarian cancer." (PMID 32390009, 2020). "Blockade of PDK4 suppressed activation of STAT3/AKT/NF-κB pathway to inhibit the cancer stem cell characteristics and glycolysis of ovarian cancer." (PMID 35543351, 2022). "Among them, PDK4 is the most widely distributed PDK isoform whose upregulation serves an oncogenic role in human colon, bladder, breast, and ovarian cancers." (PMID 35626257, 2022). "This study provides important insights supporting the therapeutic potential of targeting PDK4 via its inhibitor, DCA in the CSC subset of ovarian cancer." (PMID 32390009, 2020).
ovarian carcinoma (continued). "We demonstrated enhanced CSC characteristics of tumour cells derived from ovarian cancer ascites, concomitant with ALDH and CD44 subset enrichment and high PDK4 expression, compared to primary tumours." (PMID 32390009, 2020). "To ascertain the correlation between PDK4 overexpression and altered CSC properties in ovarian cancer, we generated transient siPDK4-transfected tumourspheres/ALDH+CD44+ cells as well as ALDH−CD44− cells transiently overexpressing PDK4." (PMID 32390009, 2020). "Ascites-derived ALDH+CD44+ tumour cell subsets endow stemness, metastatic and metabolic switch properties via PDK4-mediated STAT3/AKT/NF-κB/IL-8 signalling, suggesting PDK4 as a viable therapeutic molecular target for ovarian cancer management." (PMID 32390009, 2020). "In ovarian cancer, the expression of PDK1 and PDK4 were relatively low compared to PDK2, so we haven’t further explored whether they can phosphorylate FOXK2." (PMID 38734828, 2024). "Next, we determined whether DCA, a pharmacological PDK inhibitor, could mimic the effects of PDK4 silencing and block CSC properties in ovarian cancer cells." (PMID 32390009, 2020). "Additionally, the absence of PDK4 could motivate the EMT program and facilitate ovarian carcinoma cell migration and invasion." (PMID 34220962, 2021).
Hepatic steatosis (15 papers, 2015 to 2025). Steatosis is a term used to denote lipid accumulation within hepatocytes. "PDK4 deficiency was shown to prevent hepatic steatosis upon high-fat-diet feeding, probably due to increased PGC1⍺ activity." (PMID 36525084, 2023). "Hepatic PDK4 expression has been linked to impaired insulin sensitivity and fatty liver disease through stimulation of fatty acid uptake and synthesis in the liver." (PMID 36525084, 2023). "In conclusion, the findings of this study provide novel insights into the contribution of PDK4 to hepatic steatosis and illuminate a potential pathogenic mechanism underlying FXR mutant disease." (PMID 35251469, 2022). "However, it should also be noted that mice with Pdk4 deficiency show reduced lipogenesis and hepatic steatosis in association with a marked downregulation of genes that regulate FA uptake and synthesis as well as gluconeogenesis." (PMID 37084480, 2023). "Additionally, a causal role of PDK4 on MAM-mediated hepatic steatosis in ALD is supported by the evidence that the forced induction of MAM formation abrogated the protective effect of PDK4 deficiency in alcohol-induced hepatic steatosis." (PMID 36973273, 2023). "In the current study, CAPE alleviated fatty liver disease by increasing glucose oxidation by reducing the expression of pdk4 in adipose tissue and muscle." (PMID 40896486, 2025). "Linker introduction led to a significant increase in serum transaminase, notably ALT and worsened hepatic steatosis in ED-fed Pdk4−/− mice, indicating a reversal of the phenotype upon induction of MAM formation." (PMID 36973273, 2023). "Hepatic Pyruvate dehydrogenase kinase 4 (PDK4) levels are highly induced in human patients with NASH, whereas deletion of Pdk4 improves fatty liver in mice." (PMID 35614477, 2022). "The induction of perilipin 2 and PDK4 exemplifies the suitability of the in-vitro system to investigate drug candidates for the treatment of hepatic steatosis." (PMID 30547786, 2018). "The present study identified induced PDK4 in response to hepatic steatosis and this kinase functions as a metabolic switch between glucose and fatty acid metabolism." (PMID 30547786, 2018). "Furthermore, ED-induced hepatic lipid accumulation and triglyceride content were significantly decreased in PDK4 deficient mice, indicating that genetic ablation of PDK4 protects against the development of alcohol-induced liver steatosis." (PMID 36973273, 2023). "Increased PDK4 expression in livers of people with fatty liver disease could be a compensatory mechanism to upregulate FA oxidation." (PMID 37084480, 2023). "However, knocking out PDK4 alleviates the hepatic steatosis by regulating the activity of PDC in nonalcoholic steatohepatitis mouse models." (PMID 35030992, 2022). "In a recent study, the mRNA and protein levels of PDK4 were upregulated in NASH livers, indicating that PDK4 potentially contributes to the hepatic steatosis of NASH via regulation of several signaling pathways." (PMID 30428868, 2018). "Metformin suppresses growth hormone-mediated PDK4 expression via an AMP-activated protein kinase (AMPK)-SHP pathway and improves fatty liver disease in ob/ob mice." (PMID 29656110, 2018). "In the present study, we investigated mechanisms for improved glucose tolerance and reduced hepatic steatosis in PS10-treated (DKO) mice and PDK2/PDK4 double knockout mice fed a high-fat diet (HFD)." (PMID 29656110, 2018). "Consistently, the mRNA expression levels of fatty acid oxidation-related genes, including ACOX1, CPT1, HMGCS2, and PDK4, were increased in the livers of the MHY2013-treated db/db mice, indicating that the increased AMPK/β-oxidation signaling contributes to the improvement of hepatic steatosis." (PMID 28129657, 2017).
gastric cancer (14 papers, 2020 to 2025). A primary or metastatic malignant neoplasm involving the stomach. "Specifically, low expression levels of PDK2 and PDK4 were associated with a favorable response to ICB therapy in gastric cancer patients." (PMID 38832951, 2024). "The PDK4 inhibitor M77976 effectively diminishes metastatic potential, emphasizing the clinical relevance of PDK4 as a therapeutic target for advanced gastric cancer." (PMID 41220952, 2025). "In brief, our work demonstrated the critical function of TOP1MT in the regulation of glycolysis by PDK4 in gastric cancer." (PMID 38200513, 2024). "Subsequently, we conducted immunohistochemical staining to investigate the correlations between TOP1MT/PDK4 expression and clinicopathological characteristics in patients with gastric cancer." (PMID 38200513, 2024). "To assesse the impact of PDK on the expression of PD-L1, we conducted multiplex immunohistochemical to quantify PDK4 and PD-L1 expression in gastric cancer tissues." (PMID 38832951, 2024). "To further examine the correlation between TOP1MT and PDK4 in clinical samples, we analyzed tumor samples from 250 patients diagnosed with gastric cancer." (PMID 38200513, 2024). "The role of miR‐5683 in suppressing gastric cancer by targeting the gene pyruvate dehydrogenase kinase 4 (PDK4) has been confirmed." (PMID 39039912, 2024). "Research has verified that the upregulation of PDK4 expression enhances the ability of gastric carcinoma cells to proliferate, migrate, and invade." (PMID 39351154, 2024). "PDK4 is highly expressed in gastric cancer cells, and PDK4 is significantly correlated with tumor-infiltrating immune cells." (PMID 36362028, 2022). "Based on advanced studies, PDK4 is reported to be related to human colon, breast, ovarian, and gastric cancers." (PMID 36362028, 2022). "Compared with patients with gastric cancer and low PDK4 expression, patients with stage 1, 2, and 3 gastric cancer with high PDK4 expression had a significantly lower OS (P = 0.012, P = 0.0018, P = 0.00053, P = 0.21)." (PMID 34220962, 2021). "Compared with patients with gastric cancer with low PDK4 expression, the OS of N1 + N2 + N3 gastric cancer patients with high PDK4 expression was significantly lower (P = 1.1e-05)." (PMID 34220962, 2021). "In summary, we infer that the high expression of PDK4 is related to the poor prognosis of gastric cancer." (PMID 34220962, 2021). "Compared with patients with gastric cancer with low PDK4 expression, patients with stage N0 gastric cancer with high PDK4 expression had a significantly lower OS (P = 0.0059)." (PMID 34220962, 2021). "A latest study that included the Asian cases has also shown that PDK4 functions as an oncogene in gastric cancer, which is consistent with our study." (PMID 32780563, 2020). "Furthermore, LINC00511 overexpression enhances the proliferation of gastric cancer cells by functioning as a competing endogenous RNA (ceRNA) to regulate the miR-124-3p/PDK4 pathway." (PMID 38531930, 2024). "In gastric cancer, Linc00511 promotes progression by sponging miR-124-3p and thus targeting PDK4." (PMID 35842617, 2022). "The results showed that, compared with gastric cancer patients with low PDK4 expression, the OS of gastric cancer patients with high PDK4 expression had a significantly lower first progression survival and post-progression survival (P = 0.00036, P = 0.014, P = 5.8e-05." (PMID 34220962, 2021). "Additionally, due to the increased expression in gastric cancer, PDK4 was a probable target for the treatment of GC." (PMID 34220962, 2021). "Nevertheless, the role of PDK4 in gastric cancer (GC) occurrence and development is yet poorly understood." (PMID 34220962, 2021). "Given the importance of PDK4 in gastric cancer (GC) and its correlation with TOP1MT, this forthcoming study aims to examine the relationship between TOP1MT and PDK4 in pathology." (PMID 38200513, 2024).
gastric cancer (continued). "Our analysis revealed differential expression of glycolysis-related genes between gastric cancer tissues and normal tissues, with upregulation of PD-L1 and concurrent downregulation of HK1, PDK2, and PDK4." (PMID 38832951, 2024). "For example, in gastric cancer, LINC00511, serving as the ceRNA of miR-124-3p, regulates PDK4 expression, hence promoting the growth of tumors." (PMID 36103025, 2022).
liver cancer (14 papers, 2015 to 2024). An epithelial or non-epithelial malignant neoplasm that arises from the liver. "Regarding the link between PDK4 and m6A, Li and collaborators found that m6A -PDK4 plays an essential role in liver cancer progression." (PMID 35186927, 2022). "Our study suggested that m6A regulates glycolysis of cervical and liver cancer cells through induction of PDK4, which expanded our understanding of such interplays that are essential for therapeutic application." (PMID 32444598, 2020). "It suggested that PDK4 was involved in Mettl3 regulated growth and chemosensitivity of cervical and liver cancer cells." (PMID 32444598, 2020). "In vivo and clinical data confirm the positive roles of m6A/PDK4 in tumor growth and progression of cervical and liver cancer." (PMID 32444598, 2020). "It confirmed that PDK4 was involved in Mettl3 regulated glycolysis of cervical and liver cancer cells." (PMID 32444598, 2020). "All these data suggested that m6A regulated the mRNA stability and translation elongation of PDK4 in cervical and liver cancer cells." (PMID 32444598, 2020). "To further validate the miR-9/PPARA interaction, we examined PDK4 expression levels after miR-9 overexpression in liver cancer cells." (PMID 26206264, 2015). "In liver cancer, PDK4 has been identified as a potential tumor suppressor." (PMID 29285217, 2017). "Moreover, PDK4 promotes tumor progression in lung, cervical, and liver cancer." (PMID 34252986, 2021). "In both cervical and liver cancers, m6A modification in the 5′‐UTR of PDK4 stabilises PDK4 via the YTHDF1/eEF‐2 complex and IGF2BP3, promoting glycolysis and cancer progression." (PMID 39135292, 2024). "In cervical and liver cancer, METTL3 mediates m6A modification of PDK4 in 5’UTR, and subsequently YTHDF1 synergizes with eEF2 to promote the translation of PDK4, which in turn enhances the glycolytic process in tumors." (PMID 36830614, 2023). "In liver cancer, BRD4770 induced the expression of pyruvate dehydrogenase kinase 4 (PDK4) by epigenetic regulation of PDK4 related H3K9me2/3." (PMID 37306883, 2023).